EGFR (epidermal growth factor receptor)
Diseases named in the same sentence as EGFR in open-access papers (continued):
Sharing a sentence is not in itself a finding about the gene and the disease.
non-small cell lung carcinoma (continued). "The development of EGFR tyrosine kinase inhibitors (EGFR-TKIs) has revolutionized targeted therapy for non-small-cell lung cancer (NSCLC)." (PMID 41155547, 2025). "It has been observed that resistance to EGFR inhibitors promotes immune escape by increasing PD-L1 expression in non-small cell lung cancer (NSCLC)." (PMID 40191718, 2025). "Detection and utility of predictive biomarkers have shown clinical improvement and survival benefits for matched targeted therapies in several types of malignancies (BRAF in melanoma or EGFR in non-small cell lung cancer)." (PMID 40075591, 2025). "PARP1 has been shown to promote EGFR-TKI resistance in non-small cell lung cancer through the PI3K/AKT pathway." (PMID 40713706, 2025). "Covalent targeting of EGFR cysteine 797 by osimertinib is one of the most successful breakthroughs in targeted therapy, fundamentally transforming the treatment landscape for non-small cell lung cancer (NSCLC) patients." (PMID 41573874, 2025). "EGFR overexpression has been extensively studied due to its involvement in the development of lethal cancers, including non-small-cell lung cancer (NSCLC), and head-and-neck, breast, colon, and ovarian cancer." (PMID 40732338, 2025). "The National Comprehensive Cancer Network (NCCN) guidelines recommend EGFR-TKI therapy for patients with EGFR mutations, as it significantly improves progression-free and overall survival in EGFR-mutant non-small cell lung cancer (NSCLC)." (PMID 40740944, 2025). "Non-small cell lung cancers (NSCLCs) treated with tyrosine kinase inhibitors (TKIs) of the epidermal growth factor receptor (EGFR) almost invariably relapse in the long term, due to the emergence of subpopulations of resistant cells." (PMID 40846697, 2025). "Osimertinib, initially approved for T790M-positive non-small cell lung cancer, has shown better efficacy in LUAD with EGFR mutations when used as first-line therapy." (PMID 41189942, 2025). "Over the past two decades, marked progress has been made in treating non-small cell lung cancer (NSCLC) patients with EGFR-, ALK-, ROS1- and KRASG12C-targeted inhibitors." (PMID 40893689, 2025). "In EGFR-mutant non-small cell lung cancer (NSCLC), resistance to tyrosine kinase inhibitors (TKIs) is associated with the epigenetic silencing of the tumor-suppressive miR-483-3p." (PMID 41463366, 2025). "Epidermal growth factor receptor (EGFR) mutation detection is now commonly used in the management of cancer patients, particularly those diagnosed with non-small cell lung cancer." (PMID 40875066, 2025). "In patients with non-small-cell lung cancer, a decreased SUV (max) and increased CEA levels were associated with EGFR mutations." (PMID 40361899, 2025). "The endogenous calcium (Ca2+) channels contribute to the acquired resistance of osimertinib in epidermal growth factor receptor (EGFR) mutant non-small cell lung cancer cell lines." (PMID 39744692, 2025). "A separate study examining the development of resistance in EGFR-mutant non-small-cell lung cancers (NSCLCs) to EGFR inhibitors revealed that resistance emerged through the transformation of NSCLC to small-cell lung cancer (SCLC)." (PMID 39858036, 2025). "The sensor is designed to identify the epidermal growth factor receptor (EGFR) T790M mutation, a critical marker in non-small-cell lung carcinoma." (PMID 40724924, 2025). "We previously showed the 2-year OS rate, the primary endpoint, of 90% in a phase II trial of gefitinib induction followed by chemoradiotherapy (CRT) in unresectable, stage III, EGFR-mutant, non-small-cell lung cancer (NSCLC)." (PMID 39910007, 2025). "For example, in non-small cell lung cancer, radiomics-based models have been used to predict tumor histology, genetic mutations such as EGFR (Epidermal Growth Factor Receptor) status, and patient prognosis." (PMID 41008770, 2025).
non-small cell lung carcinoma (continued). "For instance, EGFR inhibitors, including erlotinib and gefitinib, have significantly improved outcomes in non-small cell lung cancer (NSCLC) patients harboring epidermal growth factor receptor (EGFR) mutations." (PMID 40433999, 2025). "In non-small cell lung cancer resistant to epidermal growth factor receptor inhibitors, the combination of cetuximab and CYT387 significantly inhibited proliferation." (PMID 41378297, 2025). "The activation of AXL receptor tyrosine kinase (AXL) and the concomitant EMT engender resistance to EGFR-targeting therapy in non-small cell lung carcinoma (NSCLC)." (PMID 40342734, 2025). "BAIAP2L2 promotes gastric cancer cell proliferation and metastasis via activation of AKT/mTOR and Wnt3α/β-catenin pathways, while serving as a prognostic marker in non-small cell lung cancer patients with low PD-1 and EGFR expression." (PMID 40356901, 2025). "One promising treatment strategy for non-small cell lung cancer (NSCLC) is targeted therapy targeting the epidermal growth factor receptor (EGFR)." (PMID 40728967, 2025). "Applying this approach to cfDNA from 48 non-small-cell lung cancer (NSCLC) patients, we targeted two clinically meaningful EGFR mutations: L858R and exon 19 deletion." (PMID 41154398, 2025). "Since then, a multitude of tissue based CDx tests have been approved by the United States Food and Drug Administration (FDA) in single tumor types such as BRAF V600E in melanoma and EGFR exon 19 deletions in non-small cell lung cancer (NSCLC)." (PMID 40748987, 2025). "Further analysis of EGFR gene amplification copy data from patients with non-small cell lung cancer showed that about 26% of the 3734 tested samples were detected with EGFR gene copy number alteration." (PMID 40732366, 2025). "Patients with brain metastases from melanoma, breast cancer, certain genotypes of non-small cell lung cancer (NSCLC; e.g., EGFR-activating mutations, ALK translocations), and renal cell carcinoma benefit most from a multidisciplinary approach." (PMID 41296115, 2025). "In EGFR-mutant non-small cell lung cancer, third-generation EGFR-TKIs inevitably select for on-target mutations (e.g., C797S) and bypass signaling (e.g., MET/ERBB), undermining long-term control." (PMID 41275311, 2025). "For instance, in non-small cell lung cancer (NSCLC), patients receiving EGFR inhibitors like osimertinib often relapse due to the emergence of EGFR C797S resistance mutations." (PMID 40564985, 2025). "Background/Objectives: Signaling imbalances involving epidermal growth factor receptor (EGFR) and aldose reductase (ALR2) are frequently associated with the biology of several solid tumors, including non-small-cell lung cancer (NSCLC) and breast cancer." (PMID 41599651, 2025). "For instance, icotinib, an EGFR-tyrosine kinase inhibitor (TKI), is used to treat non-small-cell lung cancer (NSCLC) with epidermal growth factor receptor (EGFR) mutation." (PMID 40078288, 2025). "This study aimed to investigate the synergistic anti-cancer effects of Melittin, a bee venom peptide, in combination with Erlotinib, an EGFR inhibitor, in non-small cell lung cancer (NSCLC)." (PMID 40243485, 2025). "Recent studies have reported the design of dual-targeted LSD1/EGFR inhibitors, demonstrating efficacy in preclinical models of non-small cell lung cancer." (PMID 41497449, 2025). "Gefitinib inhibits the epidermal growth factor receptor (EGFR) and was developed as a cancer therapy, particularly for advanced non-small cell lung cancer." (PMID 39913623, 2025). "Most of the studies proposed the AI-based models for the identification of Epidermal growth factor receptor (EGFR) biomarker in non-small cell lung cancer (NSCLC), followed by Programmed death-ligand 1 (PD-L1) and anaplastic lymphoma kinase (ALK)." (PMID 40078179, 2025). "A recent case report has identified EML4-ALK variant 3a/b as a mechanism of acquired resistance to osimertinib in a patient with EGFR L858R-positive non-small cell lung cancer." (PMID 41357203, 2025).
non-small cell lung carcinoma (continued). "EGFR-TKI-resistant non-small-cell lung carcinoma (NSCLC) cell lines are characterized by an accumulation of LD and overexpression of Stearoyl-CoA Desaturase 1 (SCD-1), a key enzyme converting saturated fatty acids into unsaturated fatty acids." (PMID 39886047, 2025). "In approximately 40%–60% of Chinese patients with non-small cell lung cancer (NSCLC), mutations in the EGFR gene are present, enabling them to benefit from treatments involving epidermal growth factor receptor tyrosine kinase inhibitors (EGFR TKIs)." (PMID 41164138, 2025). "In gefitinib-resistant epidermal growth factor receptor (EGFR)-mutant non-small cell lung cancer (NSCLC), lactate is overproduced by the upregulation of GLUT1, HK2, and LDHA." (PMID 40725147, 2025). "Currently, osimertinib, a third-generation EGFR TKI, is the standard of care for first-line therapy in patients with EGFR-mutant non-small cell lung cancer (NSCLC) that harbors common EGFR mutations." (PMID 40725428, 2025). "Background/objectives: Lung adenocarcinoma, the most prevalent type of non-small cell lung cancer, consists of two driver mutations in KRAS or EGFR." (PMID 40299444, 2025). "Epidermal growth factor receptor tyrosine kinase inhibitors (EGFR-TKIs) have demonstrated remarkable efficacy in treating non-small cell lung cancer (NSCLC), but acquired resistance greatly reduces efficacy and poses a significant challenge to patients." (PMID 40003951, 2025). "Non-small cell lung cancer (NSCLC) involves complex alterations in the epidermal growth factor receptor (EGFR) signaling pathway." (PMID 40486879, 2025). "Amivantamab (EGFR/MET) combines receptor inhibition with ADCC and has shown efficacy in non-small-cell lung cancer with EGFR exon-20 insertions." (PMID 41262250, 2025). "As a result, EGFR has become a significant immunotherapy target, particularly in colorectal cancer, non-small cell lung cancer (NSCLC), and head and neck squamous cell carcinoma." (PMID 40265416, 2025). "Oncogenic mutations in EGFR often result in EGF-independent constitutive activation and aberrant trafficking and are associated with several human malignancies, including non-small cell lung cancer." (PMID 40259053, 2025). "As a third-generation EGFR tyrosine kinase inhibitor, furmonertinib has established its role as a first-line treatment for advanced EGFR-mutant non-small cell lung cancer, demonstrating a generally favorable safety profile." (PMID 41585870, 2025). "Osimertinib, a third-generation epidermal growth factor receptor (EGFR) tyrosine kinase inhibitor (TKI), is widely used in treating patients with EGFR-mutated non-small-cell lung cancers (NSCLCs), especially in cases with secondary resistance mutations." (PMID 40422529, 2025). "For example, EGFR exon 19 deletions or L858R substitutions in non-small cell lung cancer, predict robust responses to first- and second-generation EGFR tyrosine kinase inhibitors." (PMID 41301080, 2025). "Epidermal growth factor receptor (EGFR)exon 19 deletion carriers of non-small cell lung cancer have so-called sensitized clonal lesions that respond well to tyrosine kinase inhibitors I.E. osimertinib, furmonertinib, and aumolertinib." (PMID 40183077, 2025). "Overexpression of the epidermal growth factor receptor (EGFR/HER1) is implicated in several cancers, including non-small-cell lung cancer and head and neck squamous cell carcinoma, making EGFR a well-established target for anti-cancer therapies." (PMID 40842662, 2025). "These included the “Metabolic pathways,” “EGFR tyrosine kinase inhibitor resistance,” “Non-small cell lung cancer,” “PI3K-Akt signaling,” and “B cell receptor signaling” pathways." (PMID 40224214, 2025).
non-small cell lung carcinoma (continued). "A recent meta-analysis across different therapeutics and cancer types found that women were more likely to benefit from EGFR inhibitors in non-small cell lung cancer and rituximab in non-Hodgkin’s lymphoma." (PMID 39941808, 2025). "For example, skin reactions related to epidermal growth factor receptor (EGFR) tyrosine kinase inhibitors (EGFR-TKI) for non-small cell lung cancer indicated treatment efficacy." (PMID 39681749, 2025). "For instance, YAP stimulates AXL and EGFR transcription, and accordingly reinforces cellular resistance to EGFR inhibitor and docetaxcel in non-small cell lung cancer and esophageal cancer, respectively." (PMID 40473594, 2025). "EGFR positive non-small cell lung cancer, for example, is where initially, EGFR inhibitors allow tumor regression, but eventually, the cancer grows independently from EGFR." (PMID 40149682, 2025). "Targeted molecular treatments for advanced non-small cell lung cancer (NSCLC) have been revolutionized by the identification of oncogenic activation in specific tyrosine kinases, such as EGFR, ALK, and ROS1, using driver mutations as biomarkers." (PMID 39851952, 2025). "The elevated TRPM2 expression was observed in EGFR mutant non-small cell lung cancer cell lines treated with osimertinib." (PMID 39744692, 2025). "In this study we employed a computer-guided approach to identify novel LSD1/EGFR dual inhibitors as a potential therapeutic agent for non-small cell lung cancer." (PMID 39753983, 2025). "Background/Objectives: First-generation EGFR tyrosine kinase inhibitors (EGFR-TKIs) are standard first-line treatments for advanced non-small-cell lung cancer (NSCLC)." (PMID 41155547, 2025). "Value of serum tumor markers for predicting EGFR mutations and positive ALK expression in 1089 Chinese non-small-cell lung cancer patients: A retrospective analysis." (PMID 40977824, 2025). "Tyrosine kinase inhibitors (TKIs) have transformed the treatment of epidermal growth factor receptor (EGFR)-mutant non-small cell lung cancer." (PMID 40002883, 2025). "EGFR has been shown to display resistance against ionizing radiation in the following cancers: non-small-cell lung cancer, glioblastoma, breast cancer, head and neck squamous cell carcinoma, and colorectal cancer." (PMID 41227364, 2025). "It has been used for the treatment of non-small-cell lung cancer (NSCLC), which is refractory to tyrosine kinase inhibitors (TKIs), especially for a subtype of NSCLC with EGFR mutations." (PMID 40427532, 2025). "EGFR is overexpressed in a majority of solid tumors, including those of the breast, head and neck, kidney, ovary, and colorectum as well as non-small cell lung cancer (NSCLC)." (PMID 40005958, 2025). "Non-small cell lung cancer (NSCLC) accounts for 85 % of cases and often harbors epidermal growth factor receptor (EGFR) mutations." (PMID 40290805, 2025). "Since epidermal growth factor receptor (EGFR) tyrosine kinase inhibitors were introduced in 2004, various driver gene mutations have been identified in non-small cell lung cancer, particularly adenocarcinoma, where mutations are typically mutually exclusive." (PMID 40218244, 2025). "It is one of the most common mutations in non-small cell lung cancer (NSCLC) and predicts sensitivity to EGFR-targeted therapies." (PMID 39852181, 2025). "Early-phase trials targeting HER2-positive gastric cancer and EGFR-expressing non-small-cell lung cancer showed partial responses and temporary disease stabilisation, with progression-free survival typically limited to a few months." (PMID 40906384, 2025).
non-small cell lung carcinoma (continued). "In patients with non-small cell lung cancer (NSLC) with EGFR mutations, Class II BRAF mutations are considered to play a major role in acquired resistance to EGFR inhibitors." (PMID 40977811, 2025). "Our results revealed that HDAC5, a class IIa histone deacetylase (HDAC), is a prominently induced epigenetic regulator in several EGFR-mutant non-small cell lung cancer (NSCLC) cell lines during the early response to osimertinib." (PMID 40290805, 2025). "The most significant progress has been observed in melanoma and certain subtypes of non-small cell lung cancer (NSCLC), such as those with EGFR mutations or ALK translocations." (PMID 41296115, 2025). "Evaluating response to epidermal growth factor receptor (EGFR)-tyrosine kinase inhibitors (TKIs) is crucial in non-small cell lung cancer (NSCLC) patients with brain metastases (BM)." (PMID 40438144, 2025). "Erlotinib, an EGFR-targeting tyrosine kinase inhibitor, was approved as a second-line treatment for non-small-cell lung cancer in 2004." (PMID 39822281, 2025). "Another illustrative case is the dual inhibition of epidermal growth factor receptor (EGFR) and ERK in EGFR-mutant non-small cell lung cancer." (PMID 40961924, 2025). "The therapeutic landscape for brain metastases in EGFR and ALK-mutated non-small cell lung cancer has been fundamentally transformed by the advent and evolution of tyrosine kinase inhibitors." (PMID 40981198, 2025). "For example, a previous study performed immunohistochemistry using anti-EGFR E746-A750 del and anti-EGFR L858R antibodies, which showed high specificity (99.0 and 89.7%, respectively) in non-small cell lung cancer tissue samples." (PMID 41040516, 2025). "EGFR frequently exhibits overexpression or mutations across various malignancies, including HCC, non-small cell lung cancer, breast carcinoma, pancreatic adenocarcinoma, nasopharyngeal carcinoma, and head and neck squamous cell carcinoma." (PMID 40883741, 2025). "Prior studies have explored EGFR prediction primarily in non-small cell lung cancer using PET/CT or multiparametric MRI, achieving AUCs ranging from 0.61 to 0.85." (PMID 41179692, 2025). "A clinical trial at Xinqiao Hospital of the Third Military Medical University investigated the clinical benefits of the combination of ginsenoside and an EGFR-TKI in the treatment of advanced non-small cell carcinoma in patients." (PMID 40535810, 2025). "Aumolertinib is a novel third-generation epidermal growth factor receptor tyrosine kinase inhibitor (EGFR-TKI) with proven efficacy and safety for untreated non-small-cell lung cancer (NSCLC) patients with EGFR sensitizing mutations (EGFRm) in China." (PMID 40535140, 2025). "EGCG acts as a tyrosine kinase inhibitor (TKI) in non-small cell lung cancer (NSCLC), specifically targeting the epidermal growth factor receptor (EGFR), which is often overexpressed or mutated in cancer cells." (PMID 40161336, 2025). "Recent advancements in targeted therapies for non-small-cell lung cancer (NSCLC), specifically focusing on epidermal growth factor receptor (EGFR) mutations, have revolutionized treatment strategies." (PMID 39202551, 2024). "YAP regulates epithelial-to-mesenchymal transition (EMT)-induced resistance to EGFR TKI in non-small cell lung cancer (NSCLC) via FOXM1/SAC pathway." (PMID 38164167, 2024). "We evaluated outcomes in non-small cell lung cancer (NSCLC) patients who presented with brain-only metastatic (BOM) disease overall and by EGFR/ALK mutation status." (PMID 39296139, 2024). "Recombinant humanized monoclonal antibodies and VEGFR/EGFR tyrosine kinase inhibitors (TKIs) have been widely applied in the treatment of metastatic colorectal cancer, glioblastoma, as well as non-small-cell lung cancer." (PMID 38787372, 2024). "Delphinidin reduces cell proliferation and induces apoptosis of non-small-cell lung cancer cells by targeting EGFR/VEGFR2 signaling pathways." (PMID 38716355, 2024).